SNORA74D (small nucleolar RNA, H/ACA box 74D)
Gene: Small nucleolar RNA gene on chromosome 5 (139,276,180 to 139,276,320, forward strand). Ensembl gene ENSG00000252213.
Homologues: Orthologues: chimpanzee SNORA74 (100% identical), guinea pig SNORA74D (87% identical), mouse Gm54507 (62% identical), zebrafish SNORA74 (45% identical), zebrafish SNORA74 (40% identical). Paralogues in human: SNORA74 (87% identical), SNORA74A (51% identical), SNORA74 (50% identical), SNORA74C-1 (50% identical), SNORA74C-2 (50% identical), SNORA74B (46% identical), SNORA74 (34% identical), SNORA74 (33% identical).